VDR (vitamin D receptor)
Diseases named in the same sentence as VDR in open-access papers (continued):
Sharing a sentence is not in itself a finding about the gene and the disease.
tumor (continued). "Specifically, VDR downregulates the expression of β-catenin, cyclin D1 and LEF-1 in vitro, and xenografts established by VDR-overexpressing SW480 cells shows suppression of tumor growth and decreased expression of β-catenin, cyclin D1 and LEF-1." (PMID 40630116, 2025). "We hypothesized that VD3 regulates Th17 cell differentiation through VDR’s influence on OPN, potentially affecting tumor progression." (PMID 40894304, 2025). "Acquired gefitinib-resistant NSCLCs upregulate their own VDR protein expression, which may induce CYP24A1 production and accelerate the catabolism of 1,25(OH)2D3, thereby suppressing the anti-tumor effects of 1,25(OH)2D3." (PMID 40872626, 2025). "This overexpression of VDR in PC cells promotes the recruitment and polarization of macrophages into M2 macrophage phenotype via the secretion of CCL20, which leads to the activation of tumor progression." (PMID 41009006, 2025). "Macrophages as the most abundant immune cells within the tumor, we hypothesized that PAAD cells overexpressing the VDR could promote more TAMs infiltration, thereby influencing the malignant evolution of PAAD." (PMID 38600588, 2024). "Moreover, it interferes with β-catenin-mediated gene transcription, primarily by promoting Vitamin D receptor (VDR) binding to β-catenin, emphasizing its suppressive role on tumor growth." (PMID 38542719, 2024). "Additionally, upon more extensive analysis, a significant correlation was identified between VDR expression and CCL20 expression, with CCL20-positive cells also being surrounded by higher M2/M1 ratios in the 200 μm of tumor and stroma." (PMID 38600588, 2024). "Significantly longer OS was observed in cases with high tumor VDR expression compared to those with low or no VDR expression (p = 0.037)." (PMID 39683479, 2024). "High expression of VDR in the cytoplasm of tumor cells (IRS ≥ 8) appeared to be prevalent in cases without vascular invasion and lymph node metastases." (PMID 39411136, 2024). "Correspondingly, the presence of other pathological prognostic markers of unfavorable prognosis such as ulceration or absent or non-brisk tumor-infiltrating lymphocytes (TILs) was characterized by significantly lower VDR expression." (PMID 38927967, 2024). "Melanoma cells with active VDR signaling and a suppressed Wnt-beta catenin pathway show increased tumor antigen release, antigen presentation, CD4+ T cell activation and priming, and increased CTL and NK infiltration and tumor cell killing." (PMID 37175993, 2023). "Furthermore, the expression of TPO and TSHR in VDR overexpressed tumors was increased than those in control tumors, indicating that VDR promotes DTC tumor differentiation." (PMID 35099410, 2022). "In the inflammatory model of tumorigenesis, DSS did not induce tumor development in any of the Apc+/+VDR+/+ or Apc+/+VDR−/− rats examined (six rats/genotype/sex)." (PMID 35662320, 2022). "Nor can they represent a high variability in tumor characteristics or their ability to circumvent VDR-mediated inhibition in the long term." (PMID 36364774, 2022). "Experiments demonstrated the potential of VDR agonists to set the CAFs back to a less pro-tumoral phenotype, highlighting the capability of calcitriol to exert a part of its anti-tumor activity, independent of the VDR status in tumor cells." (PMID 36364774, 2022). "There was a non-significant trend of high-grade tumours towards the low nuclear VDR expression (p = 0.07)." (PMID 36362766, 2022). "Tumors that do not express VDR any more and, thus, lose their susceptibility to calcitriol might be seen as being less affected by a vitamin D-based treatment since the expected anti-tumor effect is reduced to calcitriol’s impact on fibroblasts and immune cells." (PMID 36364774, 2022). "In summary, while PPARA, VDR, SLC16A1 and PAPSS2 supply the building blocks to synthesize macromolecules, GPX1 provides redox defense to counteract oxidative stress produced as a consequence of the high proliferation rates of tumor cells." (PMID 35565211, 2022).
tumor (continued). "In addition, low expression of VDR and CYP27B1 and high expression of CYP24A1 were observed in EAC tumor tissues compared to normal esophageal tissues." (PMID 36142861, 2022). "1,25(OH)2D3 upregulates PDL1 and PDL2 and CTLA4 by direct transcriptional induction through the VDR and VDRE It has been suggested that elevated vitamin D3 signalling in humans could suppress anti‐tumour immunity via increased PDL1 expression." (PMID 35445563, 2022). "This is given without the reference to tumour VDR signalling status, and there is no warning about using high dose vitamin D3." (PMID 35445563, 2022). "When the TN subtype was subdivided according to the basal CK expression, 9/18 basal-like TN tumours (50.0 %) expressed VDR protein, whereas 2 non basal-like TN did not express it." (PMID 34034728, 2021). "On the other hand there is inverse association between positive VDR expression in tumor cells and negative and low CTLA4 expression in tumor cells (P= 0.03 and 0.01 respectively)." (PMID 33906311, 2021). "In addition, IHC staining displayed lower expression of VDR and NAT2 in tumor tissues than matched normal tissues and simultaneous alteration of the two proteins in 19 cases, among which three typical cases were displayed." (PMID 34867333, 2021). "VDR expression was absent in HER2-overexpression tumours and low in luminal A and B molecular subtypes." (PMID 34034728, 2021). "Although speculative, it is possible that the unique CNA enrichments in these tumor subtypes (ER–/HER2– and HER2+) activate pathways that corrupt VDR signaling sufficiently to abrogate the anticancer effects of 1,25D." (PMID 34950835, 2021). "Clearly, VDR activation in tumors requires ligand, which depends on the patient's overall vitamin D status as well as the relative activity of CYP27B1 and CYP24A1 within individual tumor cells." (PMID 34950835, 2021). "When VDR KO mice were exposed to UVR, they showed greater stimulation of carcinogenesis than their wild-type siblings, and tumor proliferation continued to increase for at least 48 h, while tumor proliferation in wild-type mice reached a plateau after 24 h." (PMID 34206371, 2021). "Survival time was only correlated with tumor stage (correlation coefficient = −0.423, P value < 0.05), but was not correlated with the expression of VDR, Ki67, and CK18." (PMID 34881266, 2021). "Likewise, RXR/RXR and VDR/RXR heterodimers also regulate the expression of IGFBP1, a tumor suppressor gene that was differentially expressed in at least 4 FRCs (IPP, TiBP, TDBPP, TBBPA)." (PMID 33898466, 2021). "Whereas tumors with indicators of poor prognosis like ulceration or non-brisk or absence of tumor-infiltrating lymphocytes, showed significantly lower VDR expression." (PMID 34692525, 2021). "Survival time was only correlated with tumor stage, but was not correlated with the expression of VDR, Ki67, and CK18." (PMID 34881266, 2021). "Indeed, gene set enrichment and leading-edge analyses of activated, (shared) tissue, inflammatory and tumor-infiltrating Treg cell gene sets amongst others revealed sharing of the core eTreg cell genes, including BATF, CCND2, CCR8, TNFRSF18, and VDR." (PMID 33976194, 2021). "Likewise, treating activated stellate cells with a nuclear vitamin D receptor (VDR) ligand was sufficient to reprogram them towards a more quiescent phenotype and reduced overall tumor progression." (PMID 34359678, 2021). "Here, we detected a modest correlation between expression levels of MALAT1 and VDR in tumor tissues but not in ANCTs." (PMID 32514489, 2020). "In addition, VDR overexpression increased the sensitivity of CRC stem cells to oxaliplatin and partially attenuated the acidic tumor microenvironment-mediated promotion of drug resistance." (PMID 32900990, 2020). "Therefore, clarification of the effects of vitamin D and VDR on the stemness of CRC stem cells and elucidation of the interaction between CRC stem cells and the acidic tumor microenvironment are important." (PMID 32900990, 2020).
tumor (continued). "Because low VDR expression may hinder anti-tumor activities of VD3, it will be important to develop strategies to induce increased VDR expression." (PMID 30961641, 2019). "To test the hypothesis of VDR-mediated curcumin uptake, we analysed the VDR expression in HT29 cells and we found that this expression was higher than in other tumour cell lines and human lymphocytes." (PMID 30759785, 2019). "Different studies have described several mechanisms through which VDR can inhibit tumor growth including genomic and non-genomic signal transduction pathways." (PMID 30157901, 2018). "Although 4T1 cells express VDR, they are not sensitive to calcitriol in vitro nor in vivo; cell proliferation and primary tumor growth was not affected upon the treatment." (PMID 30037009, 2018). "Although 25(OH)-VitD plasma levels were not significantly different between controls and tumor-bearing mice, VDR protein expression was increased in the skeletal muscle of the latter." (PMID 28423519, 2017). "Increased expression of VDR and FGF23 relative to other VRS components is interesting, especially in the context of increased Runx2 expression as previously observed in the same OS-core type, and also in the tumor tissue isolated from the BOOM model." (PMID 28300755, 2017). "The other way round, the present study shows that increased VDR levels in the muscle of tumor-bearing animals seems a constant finding, irrespective of changes in circulating VitD levels." (PMID 28423519, 2017). "Furthermore, high levels of LSD1 and VDR proteins promote tumor growth in the CWR22 xenograft model of PCa, indicating a potential combinatorial role of VDR and LSD1 in promoting tumor establishment and progression." (PMID 28811844, 2017). "In contrast, only 2 out of 9 mice inoculated with VDR-KD cells developed histologically identifiable tumors, while in the remaining 7 mice no tumor was present." (PMID 28460457, 2017). "Higher CaSR expression was significantly associated with lethal progression among cases with lower tumor vitamin D receptor expression but not among cases with high tumor vitamin D receptor expression." (PMID 27625611, 2016). "To fill this gap in knowledge, we analyzed nuclear VDR expression in tumor cores from lifetime never-smokers that had corresponding DNA available for targeted sequencing of the EGFR gene." (PMID 26654942, 2016). "In cases with the lack of high cytoplasmic VDR staining the non-classic differentiations (NDs) was observed in higher percentage of tumor area." (PMID 26501255, 2015). "According to the classical pathway, vitamin D3 acts through the VDR, as supplementation of VDR knockout animals with vitamin D3 analogues does not protect them from tumor development." (PMID 26260259, 2015). "In addition, we attempted to correlate VDR expression with that of RXR and markers for tumor proliferation (Ki-67), apoptosis (survivin), progression, and metastasis (ezrin)." (PMID 23346460, 2012). "Vitamin D receptor is strongly expressed in tumor cells of HL, regardless of the sub entity with an overall positivity of 80% of all HL cases." (PMID 22672495, 2012). "As vitamin D3 acts as an inhibitor of IL1-β release, its activity was prevented by exogenous IL1β and was dependent on the expression of VDR on macrophages and not on tumor cells (data not shown)." (PMID 20661477, 2010). "Silencing of VDR by VDR specific siRNA in macrophages did not affect their ability to inhibit TRAIL-induced apoptosis in tumor cells, however vitamin D3 failed to restore TRAIL induced apoptosis of tumor cells cocultured with VDR deficient macrophages." (PMID 20661477, 2010).
tumor (continued). "If VDR/β-catenin interactions stimulate HF differentiation, then EB1089 may inhibit β-catenin induced tumour formation." (PMID 18213391, 2008). "Attempts were made in the present study to obtain snap frozen biopsies from tumours for the determination of VDR by Western blot where possible, although this was not an entry criterion for the study." (PMID 12865912, 2003). "Vitamin D (via VDR activation) was shown to inhibit EMT and ROS (reactive oxygen species) signaling—key drivers of metastasis and tumor survival—and thus may indirectly modulate stromal fibroblasts toward a less tumor-supportive state in osteosarcoma xenograft models." (PMID 40959080, 2025). "It was found that the expression level of VDR in CC was significantly higher than that in adjacent tissues, and the same results were found in the GEPIA and Oncomine database, which indicated that tumor cells would have a superior response to vitamin D than the normal tissues." (PMID 39753527, 2025). "Moreover, functional VDR elements have been identified in the promoters of phosphatase and tensin homologues (PTEN), a potent tumor suppressor, suggesting that vitamin D may be involved in the regulation of PTEN expression." (PMID 40630116, 2025). "Indeed, we found that despite low general global correlation between mRNA and protein levels that many of the novel markers we identified in our in vitro model were also up-regulated in the tumor resident T cells, including p300, ZEB2, VDR, and many SLC transporters." (PMID 39689157, 2024). "By comparing VDR expression levels in normal, benign, and malignant tissues of skin, breast, ovarian and prostate, it was described a negative correlation between VDR expression and tumor malignancy." (PMID 38666921, 2024). "Thus, in the second step, we focused on the analysis of the TCGA HNC cohort (n = 604) showing upregulation of VDR in tumor versus non-tumor tissues (n = 564, p = 0.0059 **)." (PMID 36902107, 2023). "Additionally, statistical analysis indicated that VDR expression was not significantly correlated with sex, age, tumour location, tumour size, general type, or degree of differentiation of CRC patients." (PMID 37046222, 2023). "Binding of vitamin D to VDR resulted in decreased expression of immune checkpoint inhibitors (PD-1, TIGIT, and Tim-3) and increased expression of the co-stimulatory molecule CD28 on CD8+ T cells, which increased their cytokine production and anti-tumor activity." (PMID 37175993, 2023). "However, the findings of high VDR expression were related to the tumour versus benign tissues and did not explore the relationship of vitamin D activity or VDR with tumour progression or prognosis." (PMID 35807774, 2022). "Moreover, in bone metastases, we found a non-significant trend in poor differentiated tumours towards low nuclear VDR expressions." (PMID 36362766, 2022). "Furthermore, an association between the expression of VDR and SNGH16 was reported in both tumor and nontumor tissues." (PMID 35328609, 2022). "Furthermore, in the current study, circulating 25(OH)D3 is reduced by about two-thirds in VDR-knockout rats compared to wild-type counterparts, yet did not negatively impact tumor outcome." (PMID 35662320, 2022). "However, TUNEL staining was not significantly different between the two groups, suggesting that VDR inhibits the DTC tumor growth and cell proliferation but does not affect apoptosis." (PMID 35099410, 2022). "However, we have shown no deleterious effect on tumor multiplicity, size, nor pathology in animals lacking both proper Apc and VDR expression, excluding a ligand-independent role for VDR in intestinal tumorigenesis in this model." (PMID 35662320, 2022). "Moreover, there is a trend of significance between positive VDR in the tumor cells and absent vascular invasion and absent metastasis (P value= 0.06 and 0.09 respectively)." (PMID 33906311, 2021).
tumor (continued). "In the current study there is significant association between high VDR tumor expression and parameters of good prognosis as low tumor stage (T1) and (N0) nodal stage, Moreover, there is a trend of significant between positive VDR in the tumor cells and absent vascular invasion and metastasis." (PMID 33906311, 2021). "Moreover, a negative correlation between VDR expression and tumor malignancy has been shown during the analysis of VDR expression levels in normal, benign, and malignant tissues of ovarian, breast, skin and prostate." (PMID 34208589, 2021). "However, there is no data on expression of VDR in context of quantity of FOXP3 expressing cells in CHL tumor microenvironment." (PMID 32513132, 2020). "Comparing VDR expression levels in normal, benign, and malignant tissues of skin, breast, ovarian, and prostate revealed a negative correlation between VDR expression and tumor malignancy." (PMID 29657326, 2018). "Indeed, the importance of the vitamin D receptor (VDR) in regulating cellular proliferation and differentiation was verified when the skin of mice lacking the VDR was reported to be susceptible to tumour formation." (PMID 28894263, 2017). "The first is inducing sufficient activation of tumor VDR without adverse systemic side effects." (PMID 28591703, 2017). "Carling and coworkers reported a correlation between tumor VDR levelsand patient serum calcium, but neither this study nor Varshney and coworkers could confirm thesefindings." (PMID 26865585, 2016). "At this point we have not observed tumor formation in the skin of mice lacking only the Casr, but have observed that mice lacking both Casr and VDR develop tumors of greater malignancy and spontaneity than seen in mice lacking only the VDR." (PMID 27462278, 2016). "Moreover, the studies with VDR knock-out mice showed that the absence of VDR in tumor-infiltrating vessels resulted in an increased content of angiogenic factors, such as HIF-1α, VEGF, Ang1 and PDGF-BB, in tumors." (PMID 26580599, 2015). "VDR immunostaining did not correlate with the histological tumor grade, or mitotic index." (PMID 26501255, 2015). "Tumor levels of active β-catenin were markedly increased in the absence of VDR." (PMID 26008979, 2015). "The lack of VDR, which has tumor suppressive functions, in SCCs from mice fed 1000 IU Vitamin D3 diet may explain the trend toward increased frequency of SCC in animals on this diet." (PMID 25191969, 2014). "Lack of CTNNB might be expected to reduce tumor formation in VDR null mouse skin, but when we bred CTNNB null mice with VDR null mice we did not see a reduction in tumor formation." (PMID 24202452, 2013). "Our study suggests VDR as a specific marker for tumor cells of HL, but not of B-NHL subtypes." (PMID 22672495, 2012). "The VDR would therefore appear to be related to both Breslow thickness and development of metastasis, but the effect on metastasis is at least partially independent of tumour thickness." (PMID 15238985, 2004). "Tissue was not available to determine VDR expression in this patient's tumour." (PMID 12865912, 2003). "Similarly, the lack of frozen tumour material also meant that determination of VDR mRNA expression was not possible in this study." (PMID 12865912, 2003). "The positive association with these immune cells, coupled with the negative correlation with tumor cell purity, suggests that the VDR may influence the infiltration and activity of immune cells within the tumor, thereby affecting tumor growth and response to therapy." (PMID 39268267, 2024).